AHR (aryl hydrocarbon receptor)
Diseases named in the same sentence as AHR in open-access papers (continued):
Sharing a sentence is not in itself a finding about the gene and the disease.
breast carcinoma (continued). "The purpose was to evaluate the prognostic impact of aryl hydrocarbon receptor (AHR) genotypes in relation to lifestyle and adjuvant treatments in breast cancer." (PMID 40646277, 2025). "CYP2W1 is induced by the AhR and ARNT pathway, as shown in experiments in which treatment of MDA-MB-468 and MCF7 breast cancer cells with AhR ligands such as 5F-203 and GW-610 increased expression of CYP2W1." (PMID 41020804, 2025). "In breast cancer, miR-494 indirectly downregulates TFPI2 by modulating E74-like factor 1 (ELF-1) and aryl hydrocarbon receptor (AHR), promoting tumor growth." (PMID 40361374, 2025). "To explore how AHR and IFN-I signalling together affect PARP7 inhibition on cancer cell proliferation, we used Py8119 and Py230 murine breast cancer cell lines derived from the MMTV-PyMT mouse model." (PMID 41432900, 2025). "TCDD affects Slug expression via AhR, thereby participating in the regulation of EMT in breast cancer cells." (PMID 40103267, 2025). "Here, we characterized the effects of RBN2397 on AHR and IFN-I signalling and cell proliferation in Py8119 and Py230 mammary cancer cell lines." (PMID 41432900, 2025). "BAY2416964 is a newly developed AHR antagonist for which there is limited knowledge of its ability to inhibit AHR activity and affect breast cancer cell proliferation, while GNF351 is well-known pure AHR antagonist." (PMID 39450255, 2024). "AhR activation has been shown to upregulate ALDH in oral cancer and breast cancer, while in triple-negative breast cancer, AhR inhibition reduced chemoresistance in ALDHhigh tumors." (PMID 38339226, 2024). "The elevated AHR levels in PMN macrophages were induced by GM-CSF, which was secreted by breast cancer cells." (PMID 39690159, 2024). "It has been demonstrated that the chemical carcinogen 3-methylcholanthrene activates AhR in CAF, which accelerates the development of breast cancer." (PMID 38434684, 2024). "AhR activation with TCDD disrupted cell–cell contact and induced migration via a c-Jun N-terminal kinase (JNK)-dependent pathway in breast cancer, which was abrogated with JNK inhibition." (PMID 38339226, 2024). "Selective aryl hydrocarbon receptor (AhR ) agonists (e.g., semaxanib) blocked IGF-2-mediated cell growth and reduced MYB expression in MCF-7 breast cancer cells." (PMID 38835346, 2024). "In this study we compared the effects of treatment with the AHR antagonists, BAY2416964 and GNF351, to that of AHR knockout in PyMT murine mammary cancer cells." (PMID 39450255, 2024). "For instance, ligand-activated AhR inhibits PI3K/AKT signaling pathways accompanied by reduced cyclin D1/D3 and cell division protein kinase 4 (CDK4) in breast cancer cells." (PMID 37241719, 2023). "TCDD also induced dimerization of AhR and RelB of the alternative NF-κB pathway and up-regulation of CXCL8 through a novel RelB/AhR response element (RelBAHRE) in macrophages and breast cancer cells." (PMID 37696458, 2023). "The AhR enhances the release of amphiregulin (AREG) and specific chemokines including granulocyte-colony stimulating factor (G-CSF), CXCL1/2/5, and CCL2/5 in the TME in human breast cancer tissue bearing BRCA1 mutation, which may facilitate the activation of protumorigenic and angiogenic TAMs." (PMID 37241719, 2023). "Lastly, we sought to delineate the role of AhR in mediating the anticancer and anti-CSC actions of miR125b-2–3p in breast cancer cells and mammospheres." (PMID 35694715, 2022). "In contrast, several publications have reported that AhR agonists and antagonists enhance and inhibit mammary carcinogenesis, respectively, and differences between the anticancer activities of AhR agonists in breast cancer may be due in part to cell context and ligand structure." (PMID 36428667, 2022). "Another report showed that heregulin enhanced AhR levels, IL-6 and IL-8 expression and also increased invasion in a HER2 overexpressing breast cancer cell line." (PMID 36428667, 2022).
breast carcinoma (continued). "Such cross-talk between AhR and NF-kB pathways has also been found to regulate AhR-mediated gene transcription of IL6 and IL8 in breast cancers." (PMID 35465323, 2022). "Collectively, our findings suggest that HER2-activated AHR upregulates ΔNp63 expression and that this signaling cascade is involved in CSC maintenance in HER2-expressing breast cancers." (PMID 36292946, 2022). "Of note, this was inhibited by the combination of an AhR inhibitor and an EGF receptor inhibitor, suggesting new therapeutic possibilities for this type of breast cancer." (PMID 36588678, 2022). "Most recently, camalexin, an indole phytoalexin and AhR agonist was shown to decrease the BCSC population of MCF7 and T47D (ER+) breast cancer cells." (PMID 36588678, 2022). "The AhRR decreases availability of functional AhR by competing for ARNT, and using transgenic mice overexpressing AhRR, it was shown that AhRR suppresses mammary tumor development and AhR-dependent growth and the inflammatory gene COX2 (±TCDD)." (PMID 36428667, 2022). "It has been reported that TCDD, BAP, pyocyanin, indoxyl sulfate, and other agonists can induce the migration and invasion of human breast cancer MDA-MB-231, Hs578T, SUM149 cells, oral squamous cell carcinoma via activating the AhR signaling pathway." (PMID 34955744, 2021). "Such cross-talk through altered p300 recruitment to Nrf2-regulated target genes was shown in ER(+) MCF7 breast cancer cells treated with racemic SFN, a combination of AhR and ERα activator, and 17β-estradiol (E2)." (PMID 33064289, 2021). "Western Blot data and mRNA expression analysis confirm the successful knockout of AhR in MCF-7 and MDA-MB 231 breast cancer cell lines." (PMID 33763068, 2021). "Transcriptional inhibition of AhR was shown to induce expression of the tumor suppressor gene E-cadherin (CDH1), reducing the mesenchymal properties of breast-cancer cell lines." (PMID 33451095, 2021). "For example, both elevated AhR expression and activity have been observed in papillary thyroid carcinoma (PTC), primary breast cancer, and cutaneous squamous-cell carcinoma." (PMID 33451095, 2021). "Yang at al. performed genome-wide mapping and analysis of AhR-binding sites in human breast cancer cells before and after induction by TCDD using ChIP-seq analysis and identified up to 4000 AhR-bound regions." (PMID 33451095, 2021). "Expression analysis confirmed that AhR as well as COX-2 and C/EBPβ were suppressed in mammary tumors of PyMT/AhRR+ mice compared to PyMT/wt mice." (PMID 33763068, 2021). "Collectively, these observations confirm the role of the AHR and CYPs in mediating the effects of NAP-6 in sensitive breast cancer cell line models." (PMID 32814815, 2020). "Previously, we showed that higher expression of AHR and PXR, the receptors for IS prolong survival in breast cancer patients." (PMID 33050543, 2020). "HPGD, hydroxyprostaglandin dehydrogenase 15‐(NAD), was found to be abundantly expressed in highly metastatic breast cancer cells, while knockdown of HPGD attenuated aryl hydrocarbon receptor signalling and induced mesenchymal‐epithelial transition." (PMID 33107155, 2020). "A higher expression of PXR and AHR supported better survival in human breast cancer patients, highlighting the importance of IPA-elicited pathways in cytostasis in breast cancer." (PMID 32854297, 2020). "In this vein, we have ascertained that the nuclear translocation of AHR induced by 3MC is abrogated in the presence of the AHR inhibitor CH223191 and the GPER antagonist G15 in breast cancer cells." (PMID 31370872, 2019). "Collectively, these findings suggest that AHR and GPER are involved in the CYP1B1 and cyclin D1 induction upon exposure to 3MC toward the growth responses observed in breast cancer cells and CAFs." (PMID 31370872, 2019).
breast carcinoma (continued). "3MC was able to trigger the co-immunoprecipitation of GPER, AHR and EGFR, thus generating a ternary complex assembly of these receptors in SkBr3 breast cancer cells toward their functional cooperation." (PMID 31370872, 2019). "Several compounds like aromatic hydrocarbons as well as estrogens can stimulate the expression of the AHR target gene CYP1B1, which is overexpressed in a variety of tumors including breast cancer." (PMID 31370872, 2019). "Altogether, our results indicate that GPER is involved in a transduction network that includes AHR and EGFR toward 3MC-induced stimulatory effects in breast cancer cells." (PMID 31370872, 2019). "To better understand the role and extent to which AHRR alters AHR action, we determined the genome-wide binding profiles of AHRR in MCF-7 human breast cancer cells using chromatin immunoprecipitation followed by next-generation sequencing (ChIP-Seq)." (PMID 28681081, 2018). "The mechanism of interaction between AhR and CYP1A1 or CYP2, where both are involved in the metabolism of estrogen which may lead to alteration in steroid levels modulating bioactivation of therapeutic agents and xenobiotics and elevating the risk of breast cancer in smoking women." (PMID 29707532, 2018). "To identify the genomic binding profiles of AHR and AHRR, we performed ChIP-Seq on chromatin isolated from MCF-7 human breast cancer cells treated with 10 nM TCDD for 24 h." (PMID 28681081, 2018). "In this study, we compared the genome-wide binding profiles of AHR and AHRR in MCF-7 human breast cancer cells treated for 24 h with TCDD using chromatin immunoprecipitation followed by next-generation sequencing (ChIP-Seq)." (PMID 28681081, 2018). "We have recently reported that LAT1 is an aryl hydrocarbon receptor (AHR) target gene and that reducing AHR or LAT1 with short interfering RNA (siRNA) reduces the proliferation of MCF7 and MDA-MB-231 breast cancer cells." (PMID 30103560, 2018). "Its effects on breast cancer were first reported in rodent models of tumorigenesis, including TCDD-induced breast tumors that express high levels of AHR." (PMID 29320557, 2018). "In an effort to better understand the AHR–AHRR signaling axis, we determined the genome-wide binding profiles of AHRR and AHR in TCDD-treated MCF-7 human breast cancer cells." (PMID 28681081, 2018). "In contrast, previous studies have reported a protective effect of AhR agonist on CSCs of TNBC and MCF-7 breast cancer cells via downregulation of Wnt/β-Catenin and Notch signaling pathway." (PMID 28103884, 2017). "This study aimed to illustrate the effects of protoberberines on aryl hydrocarbon receptor (AhR) activation and cytochrome P450 (CYP) 1 in the estrogen receptor (ER)α(+) MCF-7 breast cancer cells." (PMID 29143794, 2017). "In breast cancer cell lines, BBP promotes cancer stem cell growth through activation of the aryl hydrocarbon receptor (AhR)." (PMID 28865460, 2017). "According to these results, human breast cancer MCF-7 cell line, that showed the highest expression levels, was utilized as a study model for investigating the role of AhR/CYP1A1 pathway in regulating and controlling CSCs." (PMID 28103884, 2017). "In order to evaluate the effect of AhR pathway modulation in vivo, we used DMBA-induced breast cancer model in Balb/c mice." (PMID 28103884, 2017). "In accordance with our findings, it has been recently reported that G-1 is also able to up-regulate the expression of both AhR and CYP1B1 in ER-positive MCF-7 breast cancer cells, although the molecular mechanisms involved remain to be elucidated." (PMID 29290975, 2017). "In contrast, AhR activation by TCDD and 3.3′-diindolylmethane (DIM) regulated miR-132/212 expression in MDA-MB-231 and T47D breast cancer cells." (PMID 27243009, 2016). "Our recent findings indicate that AHR responds to and mediates IGF2 signaling in MCF7 breast cancer cells." (PMID 25699021, 2015).
breast carcinoma (continued). "Many studies have effectively utilized the AhR-agonist and mammary carcinogen DMBA to examine the molecular pathways that contribute to breast cancer and efficacy of therapies." (PMID 26715507, 2015). "CYP1A1, AHR, AR, CYP1A, CYP1B1 and PTGS2 genes are common in both PCB-gene and PCB-gene-breast cancer groups." (PMID 26512648, 2015). "β-naphthoflavone (BNF), an agonist of the AhR and a putative chemotherapeutic agent, inhibited PI3K/Akt signaling in breast cancer cells." (PMID 25625591, 2015). "Aminoflavone, a ligand of the aryl hydrocarbon receptor, is known to repress HIF-1α translation in human breast cancer cells by inducing eIF2α phosphorylation." (PMID 26474388, 2015). "To further elucidate the cross-talk between expression and/or activation of AhR, and BRCA-1 regulation, we turned to cell culture experiments using UACC-3199 sporadic breast cancer cells, which possess hypermethylated BRCA-1 promoter and express low ERα." (PMID 26715507, 2015). "Indeed, we have reported the first instance of low dose (250nM) AF treatment resulting in cellular senescence, as shown using senescence-associated β-galactosidase staining, in Cal51shAhR human breast cancer cells, both in the presence and absence of AhR knockdown." (PMID 24885022, 2014). "BRCA1 is known to bind AhR and ARNT to activate the transcription of their target genes in breast cancer cells." (PMID 24704793, 2014). "For example, activation of AhR target genes by a typical ligand of AhR, 2,3,7,8-tetrachlorodibenzo-p-dioxin (TCDD), correlated with constitutive ERα expression levels in breast cancer cell lines." (PMID 24058584, 2013). "Using highly specific AHR agonists and AHR-siRNA, we provide the first evidence suggesting that specific ligand activation of the AHR inhibits adipo-CM and IGF-2-stimulated proliferation of ER positive human breast cancer cells." (PMID 24171117, 2013). "We also report that a highly specific AHR agonist significantly (P < 0.05) inhibits the expression of E2F1, CCND1 (known as Cyclin D1), MYB, SRC, JAK2, and JUND in breast cancer cells." (PMID 24171117, 2013). "The presence of AHR, ARNT and ERα at the dioxin-inducible CYP1A1 enhancer and the E2-inducible pS2 promoter has already been documented in MCF7 cells and other breast cancer cell lines." (PMID 22235307, 2012). "In this study, we examined the role of AHR and ARNT on ERα-dependent target gene transcription in the human MCF7 breast cancer and the human ECC-1 endometrial-cervical cancer cell lines." (PMID 22235307, 2012). "For example, in human mammary tumor cell lines, AHRR knock-down with siRNA enhances AHR activity, confirming the assumption that AHRR constitutively represses AHR activity in tumors." (PMID 22952704, 2012). "Although tranilast has a much lower affinity for the AHR than 3-MC, it can induce comparable expression of CYP1A1 in breast cancer cells when added to cultures at pharmacological concentrations (≥100 μM)." (PMID 21072210, 2010). "In breast cancer, EDCs may modulate subtype-specific signaling pathways involving estrogen receptor activation, HER2 crosstalk, aryl hydrocarbon receptor signaling, and homologous recombination networks." (PMID 42316330, 2026). "Finally, T47D cells are a cancer cell line notably expressing AHR that activates CYP1A1 and CYP1B1 expression and many downstream genes frequently found in breast cancers." (PMID 41336283, 2025). "We previously showed that breast cancer patients who used antioxidants preoperatively had higher frequency of nuclear AhR positive tumours compared to non-users, indicating AhR activation." (PMID 40646277, 2025). "Metformin may act as an inhibitor of AhR and its downstream genes, as it reduces expression of CYP1A1 and CYP1B1 in MCF-7 breast cancer cells by suppressing the AhR signaling pathway." (PMID 41440753, 2025).
breast carcinoma (continued). "On the other hand, MacPherson and Matthews showed that the RNAi-mediated knockdown of ERα in T-47 D human epithelial breast cancer cells did not affect the inhibitory action of resveratrol on AhR activity." (PMID 39339278, 2024). "Furthermore, the average of the expression of TDO2, AhR, and ZEB1 genes is higher in basal-like breast cancer (TNBC) than that in luminal A/B [estrogen receptor–positive (ER+)] breast cancer and when generally comparing ER− versus ER+ tumors." (PMID 39311710, 2024). "AHR activity was determined using the EROD activity assay, a standard method for evaluating the receptor’s canonical pathway by measuring CYP1A1 induction in MCF-7 human breast cancer cells." (PMID 39204085, 2024). "Animal and cellular studies on the breast cancer cell line MCF-7 have shown that AhR expression is not necessary for mammary carcinogenesis and that the MCF-7 cell proliferation is unaffected by AhR deficiency." (PMID 38434684, 2024). "Although primary breast cancer tumors were examined in these clinical datasets for expression levels of TDO2, AhR, and ZEB1, these genes may be expressed at even higher levels in circulating tumor cells (anchorage-independent condition)." (PMID 39311710, 2024). "However, how AHR in macrophages reacts specifically to tumor cells and modulates the PMN in breast cancer are not fully understood." (PMID 39690159, 2024). "Moreover, the Gene expression-based Outcome for Breast cancer Online dataset showed that TNBC cell lines expressed a higher average of AhR and ZEB1 expression compared with that in hormone receptor–positive HER2+ breast cancer cell lines." (PMID 39311710, 2024). "On the other hand, it was demonstrated that IS is able to inhibit breast cancer cells both in vitro and in vivo through the binding with AhR and pregnane X receptor (PXR), while the enhanced expression of IS-producing enzymes is a favorable survival marker of breast cancer patients." (PMID 37372437, 2023). "In human breast cancer MCA-7 cells, hypoxia mimetic CoCl2 inhibits AhR-mediated processes." (PMID 37305351, 2023). "Elucidating the precise relationship between the AhR and IDO2 may shed light on novel therapeutic strategies for future breast cancer treatments." (PMID 37408267, 2023). "Interestingly, a recent study in a zebrafish model found that the treatment of adipocyte stem cells with the potent AhR agonist TCDD led to increased stemness and metastasis of co-cultured breast cancer cells." (PMID 37408267, 2023). "The three co-opted E3 ligases, VHL, XIAP, and AHR, have been explored against cancer targets in PROTAC12,22,44–46, and their expression patterns in tumor and normal tissues suggest extensive future usage, such as XIAP in breast cancer." (PMID 37845222, 2023). "It has been demonstrated that, in breast cancer cell lines MCF-7 and MDA-MB-231 under the influence of organophosphate pesticide chlorpyrifos (CPF) and due to the action of AhR, cell proliferation is induced and the Wnt/β-catenin signaling pathway is launched, partially via the PGE2 pathway." (PMID 37232717, 2023). "In this regard, studies by Kado and colleagues demonstrated that 2,3,7,8-tetrachlorodibenzio-p-dioxin (TCDD)-mediated activation of AhR signaling increased IDO2 expression in wildtype MCF7 breast cancer cells but not in CRISPR-cas9 AhR-knockout MCF-7 cells." (PMID 37876966, 2023). "In breast cancer cell lines (MCF-7 and MDA-MB-231) AHR was identified as a target of miR-548." (PMID 37696456, 2023). "In another study on 436 breast cancer cases, it was concluded “that AhR expression is not a prognostic factor in breast cancer”." (PMID 36428667, 2022). "In breast cancer, tranilast, a tryptophan metabolite and AhR agonist, was shown to inhibit the BCSC population in MDA-MB-231 (triple negative) breast cancer cells and abrogate metastasis in a tail vein injection model, in an AhR dependent manner." (PMID 36588678, 2022).